EZH2 (enhancer of zeste 2 polycomb repressive complex 2 subunit)
Diseases named in the same sentence as EZH2 in open-access papers (continued):
Sharing a sentence is not in itself a finding about the gene and the disease.
cancer (continued). "The histone H3 lysine 27 (H3K27) methylation status is dominated by histone methyltransferase EZH2 and two lysine demethylases (KDMs), and deregulated H3K27 methylation is often associated with a multitude of cancer types." (PMID 34950587, 2021). "EZH2 enhances cell proliferation and is widely found in cancers, including renal cancer, breast cancer, prostate cancer, and lymphoma." (PMID 35008848, 2021). "EZH2 hyperactivity and deregulated H3K27me3 are also correlated with poor prognosis in several cancer subtypes." (PMID 34503063, 2021). "Overexpression of EZH2 is often correlated with advanced stages of human cancer progression and poor prognosis including TNBC." (PMID 33934088, 2021). "Experimental validation confirmed that pharmacological EZH2 inhibition increases the resistance of cancer cells to PLX4720 treatment." (PMID 33713851, 2021). "It was reported that EZH2 regulates cellular senescence through epigenetically repressing the expression of p21 in cancer cells." (PMID 33391480, 2021). "The repressive activity of EZH2 on gene expression is mostly known to promote cancer progression and contribute to therapy resistance, to metastasis and resistance to programmed cell death in numerous cancers including TNBC." (PMID 34845197, 2021). "It turns on EZH2 repressive epigenetic programs, ultimately resulting in subverting cancer cells to a stem-cell-like epigenetic state." (PMID 34356101, 2021). "EZH2 enzymatic inhibitors have impressive efficacy in certain preclinical and clinical cancer models." (PMID 34617019, 2021). "Our findings support a model by which upregulation of USP7 in cancers resulted in an elevated abundance of EZH2, as well as H2BK120ub1 removal and an increased level of H3K27me3, which is independent on the PRC1 complex." (PMID 33849069, 2021). "Allosteric EED inhibitors, PRC2 disrupters, and EZH2/EED degraders can inhibit the growth of cancers insensitive to EZH2 enzymatic inhibitors, although the full utility of these compounds remains to be explored." (PMID 34617019, 2021). "The cancer-related preferences of EZH2 for specific gene targets were also reflected in studies comparing the status of H3K27me3 in BC (MCF7 and MDA-MB-231) and normal human mammary epithelial cells (HMEC)." (PMID 34884658, 2021). "The EZH2 is involved in the maintenance and differentiation of both normal embryonic stem cells and cancer stem cells (Richly, Aloia, & Di Croce, 2011)." (PMID 32840881, 2021). "Enhancer of zeste homolog 2 (EZH2) is an enzymatic subunit of the polycomb repressive complex 2 (PRC2) that plays crucial role in cancer development." (PMID 33685449, 2021). "EZH2 was documented to be overexpressed in a wide range of cancer types, including lung, liver, prostate, and breast cancers." (PMID 33803922, 2021). "EZH2 is reportedly essential for the proliferation of cancer cell lines and for regulating the expression of genes related to EMT." (PMID 34072894, 2021). "In contrast to EZH2, several studies have demonstrated an inconsistent correlation between histone lysine modification H3K27me3 and cancer prognosis." (PMID 34944658, 2021). "EZH2 has been intensely studied in cancer, and has gained attention in generating a functional, adaptive immune response." (PMID 34464475, 2021). "Although the correlation between EZH2 overexpression and chemoresistance of human cancers or PCa progression has been reported 16, 17, 22, 41-44, the role of EZH2 in PCa chemoresistance remains to be further defined." (PMID 34093859, 2021). "EZH2 inhibition by DZNep as an epigenetic drug shows anti-proliferative, pro-apoptotic effects in cancer cells 66, and attenuates TGFβ-dependent HSCs activation." (PMID 33391480, 2021). "More and more evidences show that EZH2 is involved in the abnormal transcription of cancer cells and is related to the poor prognosis of a variety of human malignancies." (PMID 34335707, 2021).
cancer (continued). "Recent studies have shown that competitive EZH2 inhibitors can exhibit anti-cancer activity in a variety of cancers, such as 3-deazaneplanocin A." (PMID 34288823, 2021). "In contrast, the expression of EZH2 gene was upregulated in all cancer cell lines, and SW480 showed the highest level." (PMID 33879635, 2021). "miR-3613-3p was shown to inhibit the growth of TNBC cell lines by targeting SMAD Family Member 2 (SMAD2) and Enhancer of Zeste Homolog 2 (EZH2), two important genes that implicate cell proliferation and cancer growth." (PMID 34439268, 2021). "Trimethylation of lysine 27 and dimethylation of lysine 9 of histone-H3 catalyzed by the histone methyltransferases EZH2 and G9a impede gene transcription in cancer." (PMID 33632299, 2021). "Herein, in this study, the potential relationship between the infiltration level of different immune cells and EZH2 gene expression in diverse cancer types of TCGA was investigated." (PMID 34381492, 2021). "This has been observed for KDM6 (also known as UTX1) and EZH2, which are the main demethylase and methyl-transferase of H3K27, respectively; mutations in these factors are frequently detected in cancer and can change the methylation pattern at H3K27." (PMID 34298745, 2021). "The observed results clearly showed that E.C.M. detached cancer cells require oncogenic EZH2 and can be targeted by EZH2 inhibitors." (PMID 33531586, 2021). "As a result, ZMYND8 overexpression impairs EZH2 Polycomb-dependent gene repressor function but activates EZH2 Polycomb-independent gene activator function, thereby enhancing cancer migration and invasion." (PMID 33593912, 2021). "It has been demonstrated that SOX4 functions directly as a transcriptional activator of the EZH2 promoter and induces the expression of EZH2 in cancer cells." (PMID 34055896, 2021). "Together, these data highlight the potential dual function of Ezh2 inhibition on promoting cancer cell antigen presentation and Th1 chemokine production in human HNSCC." (PMID 33403469, 2021). "The progression of the cell cycle of cancer cells can inhibited upon inhibition of the EZH2 expression, and this results in upregulation of the cellular level of p21." (PMID 33934088, 2021). "In additionto appraising the EED binding by TR-FRET assay, the most potent compoundswere also tested in cancer cell lines responsive to EZH2 inhibition(i.e., G-401 and OCILY cells) to assess the impairment of the H3K27trimethylation." (PMID 34351144, 2021). "In this context, EZH2 targeting therapies, at present, have garnered significant attention for the treatment of many types of cancer." (PMID 33840388, 2021). "EZH2 is involved in the regulation of cell cycle progression and its dysregulation results in accelerated cell proliferation and cancer development." (PMID 34140011, 2021). "Given the evidence for EZH2 as a cancer driver, the development of EZH2-specific inhibitors has been an active area of investigation." (PMID 34638497, 2021). "More importantly, the lncRNA-induced miRNA suppression in cancer progression was recently shown to be mediated by EZH2, which directly represses miR-214 expression in cervical cancer." (PMID 33589600, 2021). "As well as Ezh2, among the target genes of miR-124 in cancer cell, polypyrimidine tract-binding protein 1 (Ptbp1; PTB1 gene in humans) is known to be associated with such an effect." (PMID 34072894, 2021). "These transcriptional events actually correlate with an enhanced accumulation of monocytes in MCS that, due to their protumoral phenotype, curb the antiproliferative effects of EZH2 inhibition in cancer cells." (PMID 33922336, 2021). "Inhibition of epigenetic modifications such as HDAC, EZH2, and PARP has been recently proven to be associated with immune evasion and immunomodulatory effects in BCa and other malignant tumours." (PMID 34154613, 2021). "EZH2 is a core subunit of the Polycomb Repressive Complex 2 (PRC2), which is associated with cancer." (PMID 35052383, 2021).
cancer (continued). "While EZH2 phosphorylation is highly implicated in its role in gene activation and cancer progression, how EZH2 phosphorylation is leveraged by other signaling pathways to contribute to cancer progression has remained unexplored." (PMID 33593912, 2021). "In recent years, EZH2 has become a popular target for cancer therapeutics, and the research of EZH2 inhibitors and their combined application with other antitumor drugs in clinical practice has broad prospects." (PMID 34737956, 2021). "By targeting NFIB, a well-studied metastatic driver, a regulator of EZH2, and downstream effector of c-Myc, miR-212-3p decreased cancer cell aggressiveness, stem cell maintenance, and renewal." (PMID 34922631, 2021). "The target genes of EZH2 are generally oncosuppressor genes or those involved in cell differentiation; its deregulation promotes uncontrolled cell proliferation and thus cancer progression." (PMID 34372908, 2021). "EZH2 is now considered as a potential target for cancer therapy, and different types of EZH2 inhibitors have been developed which are being evaluated in clinical trials." (PMID 34815475, 2021). "The activity of EZH2 depends on multiple metabolites and targeting of EZH2 affects the metabolism of cancer cells." (PMID 33579905, 2021). "EZH2 is an oncogenic factor commonly upregulated in human cancers, while DLC1 is a downregulated tumor suppressor in many malignant tumors." (PMID 34680593, 2021). "Targeting EZH2 to treat cancer is a hot spot in current clinical research and some inhibitors have been approved by FDA to treat cancer." (PMID 34671029, 2021). "In this review, we discuss the current knowledge of the functions of EZH2 in T cell development, differentiation, and function and its potential value in cancer treatment and immunotherapy." (PMID 34737746, 2021). "Studies in multiple cancer types have validated the effect of Ezh2 on MHC class I antigen presentation, including HNSCC." (PMID 33403469, 2021). "EZH2 not only promotes the formation of cancer stem cells, but also expands the aggressive cancer cell population and leads to cancer progression." (PMID 33985534, 2021). "The ChIP analysis on the PD-L1 promoter region indicated that the BRM recruitment in control CD4+ T cells was replaced by BRG1 and EZH2 in CD4+ T cells strongly exhausted by cancer cells." (PMID 34439305, 2021). "Expression analysis of treated tumors identified a number of differentially expressed genes including decreased expression of pediatric cancer markers and EZH2 targets only after combined treatment." (PMID 34654445, 2021). "It has been proposed that the role of EZH2 in cancer is related to its activity in promoting self-renewal and maintaining the undifferentiated state of cells." (PMID 34372908, 2021). "The results showed that levels of most of the immunosuppressive cytokines, such as Arg2, CCL28, DNMT1, and EZH2, were upregulated in the high-risk subtype, suggesting that high-risk A-HCC patients have reduced cancer-immunity cycle activity." (PMID 34512165, 2021). "EZH2 is expressed in many cancer types in correlation with advanced disease stage and high proliferation index." (PMID 34638497, 2021). "Elevated expression of EZH2 is a distinct feature of these cancer types and is often correlated with a poor prognosis." (PMID 33849069, 2021). "EZH2, a polycomb group protein, is involved in cancer progression, and its expression provides an early marker of precancerous changes in histologically normal mammary tissue." (PMID 33934088, 2021). "Three recent studies have investigated the potential of using inhibitors of EZH2 to enhance cancer immunity and immunotherapeutic efficacy." (PMID 34930302, 2021). "By modulating gene expression, EZH2 promotes the survival, proliferation, and invasion of cancer cells, in addition to enhancing the development of drug resistance among these cells." (PMID 33778063, 2021).
cancer (continued). "The emerging and diverse roles of EZH2 in human cancers mainly derive from its transcriptional, post-transcriptional and post-translational modulations of gene expression." (PMID 33664859, 2021). "The differences in EZH2 phosphorylation levels in different malignant tumors were also compared by using the CPTAC dataset." (PMID 34381492, 2021). "EZH2 is commonly known to promote the progression of diverse human cancers by H3K27me3-mediated silencing of tumor suppressors." (PMID 35372800, 2021). "Since the EZH2, a catalytic component of PRC2, functions as a histone methyltransferase, EZH2 by epigenetic modification of histone H3 can regulate various genes and has a significant role in cancer progression and development." (PMID 33805687, 2021). "In various cancer cells, EZH2 is known to play a critical role in the maintenance and expansion of stem cell-like characteristics through activation of stemness-associated signaling pathways." (PMID 34771469, 2021). "Among these patients, the most frequently altered gene was EZH2, which encodes the histone methylase H3K27—an epigenetic silencer that regulates gene expression in numerous cancers." (PMID 33778063, 2021). "EZH2 inhibition induced upregulation of class I antigen presentation in multiple MHC-I low cancer types, which subsequently sensitized cancer cells to T cell-mediated killing." (PMID 33403469, 2021). "EZH2 is another attractive target for anti-cancer therapy because of its ability in promoting the division and proliferation of cancerous cells and role in regulating immune cells in TIME, including T cells, NK cells, DCs and macrophages." (PMID 33868269, 2021). "EZH2 is one of the most important epigenetic regulators which has been shown to be involved in multiple types of cancer." (PMID 34093860, 2021). "Results showed both EZH2 expression and its enzymatic activity were significantly increased in E.C.M. detached cancer cells when compared to the attached cells." (PMID 33531586, 2021). "Given the evidence for EZH2 enzymatic gain of function being a cancer driver, inhibition of EZH2 has been thought of as a novel and promising approach for cancer therapy." (PMID 34054126, 2021). "EZH2 methyltransferase inhibition results in decreased proliferation, suggesting that decreased H3 methylation has a protective effect on the cancer development." (PMID 33478063, 2021). "EZH2 was proved to be closely related to cancer initiation, progression, metastasis, and drug resistance." (PMID 33712026, 2021). "EZH2 overexpression is frequently found in various human cancers including breast, prostate, and bladder cancer." (PMID 34358125, 2021). "Many UTX mutant cancers have increased levels of H3K27me3 and are more sensitive to EZH2 inhibitors." (PMID 34617019, 2021). "Cancer cells exhibited epigenetic silencing of KLF2 through direct transcriptional repression mediated through the EZH2–H3K27me3 axis." (PMID 34685528, 2021). "These are currently under evaluation for the treatment of various cancers, but our study suggests caution due to the immune consequences of targeting EZH2." (PMID 34464475, 2021). "The recent publication provides a strong theoretical basis to demonstrate that the dual inhibition of EZH2/EHMT2 methyltransferases can bring more effective prospects for cancer treatment." (PMID 34409024, 2021). "In many cancers, EZH2-mediated silencing of tumor suppressor genes is considered as a potential mechanism of cancer progression." (PMID 34577136, 2021). "Posttranslational modifications are distinct approaches for the adjusted modification of EZH2 in the development of cancer." (PMID 34745848, 2021). "This cytostatic effect most likely occurred via cell-cycle arrest, since it has been shown previously that gene silencing of EZH2 in cancer cell lines stopped proliferation and increased the number of cells in G1 and G2." (PMID 34638497, 2021).
cancer (continued). "Targeting EZH2 therapy has become a hot research topic in cancer treatment and here we present a potent and selective EZH2 inhibitor, SHR2554." (PMID 34503063, 2021). "It is known that the downregulation of EZH2 inhibits cancer cell growth, proliferation, and invasion." (PMID 34944867, 2021). "As an oncogene in solid cancers, EZH2 has been reported to affect many cancer-related signaling pathways and eventually promote cancer cell proliferation, malignant transformation, and survival." (PMID 34671029, 2021). "EZH2 is highly expressed in many malignant tumors including TNBCs, and elevated EZH2 expression portends a poor prognosis for patients." (PMID 33934088, 2021). "EZH2, an important regulator of cancer gene expression, interacts with class I HDACs, and its protein levels and interaction with DNMT1 are downregulated by HDAC inhibitors." (PMID 33676569, 2021). "EZH2 is a histone methyltransferase that contributes to the epigenetic silencing of target genes and regulates the cell lineage commitment and cancer progression." (PMID 33934088, 2021). "Via these three different mechanisms, EZH2 works as a hub for several pathways that are crucial for cancer development, such as cell-cycle progression, autophagy, apoptosis, DNA repair cell development, and lineage differentiation." (PMID 34638497, 2021). "Collectively, these preclinical studies suggested that targeting of EZH2 in both NK cells and cancer cells can potentially promote the NK cell-mediated killing of cancer cells." (PMID 33403469, 2021). "This elegant work has demonstrated the conserved function of PRC in negatively regulating the antigen presentation process in cancer cells and the potential of EZH2 inhibition in augmenting antitumor immunity." (PMID 33403469, 2021). "EZH2 has been reported to be dysregulated at genetic, transcriptional and post-transcriptional levels in carcinomas." (PMID 34859108, 2021). "Overexpression of EZH2 is observed in a variety of different cancers, suggesting potential therapeutic opportunities." (PMID 33371192, 2020). "For example, one of the EZH2 cancer mutants is K510R, which affects the main site of PRC2 complex automethylation." (PMID 33266419, 2020). "Inhibition of EZH2 activity is thought to be a potent treatment option for eligible cancer patients with an aberrant EZH2 expression profile, thus the indirect EZH2 inhibitor 3-Deazaneplanocin A (DZNep) is currently under evaluation for its clinical utility." (PMID 32408898, 2020). "Of note, the binding of lncRNA to EZH2 protein has been the most frequently demonstrated in various cancer processes." (PMID 33050646, 2020). "Enhancer of zeste homologue 2 (EZH2) is a key member of the polycomb group genes and is able to promote the malignancy of cancer cells via inhibiting the expression of a variety of tumor suppressor genes (TSGs)." (PMID 32545648, 2020). "Proliferation, apoptosis, cancer stem-like cells (CSCs) properties, migration and invasion were evaluated under circumstances of treatment with either EZH2 shRNA or EZH2 inhibitor GSK126." (PMID 32127003, 2020). "As a stemness factor, histone methyltransferase EZH2 has the ability to regulate cell differentiation, embryonic development, and cancer development, and EZH2 silencing has been confirmed to downregulate different genes in ESCC." (PMID 33330444, 2020). "In cancer cells, EZH2 epigenetically represses Deptor, an inhibitor of the mammalian target of rapamycin (mTOR) pathway." (PMID 32508971, 2020). "The functional regulation of EZH2 is important because of its several crucial roles in cancer progression." (PMID 33308321, 2020). "DZnep is sometimes erroneously considered to be a histone methyltransferase EZH2 inhibitor, because of the misinterpretation of a report showing that it inhibits histone methylation sites targeted by EZH2 in cancer cells." (PMID 32376902, 2020).